PPP2R1A (protein phosphatase 2 scaffold subunit Aalpha)
Diseases named in the same sentence as PPP2R1A in open-access papers (continued):
Sharing a sentence is not in itself a finding about the gene and the disease.
lung carcinoma (8 papers, 2013 to 2024). "Notably, Nelfinavir and Velnacrine exhibited significant effects on the risk model and PPP2R1A, suggesting their potential contribution to lung cancer treatment." (PMID 38654331, 2024). "Our study was unique and revealed two functional SNPs in PPP2R1A and PPP2R5E were associated with increased risk of lung cancer." (PMID 24204789, 2013). "In conclusion, our data suggested that the two functional SNPs (rs11453459->G of PPP2R1A and rs1255722A >G of PPP2R5E) are associated with risk of lung cancer in Chinese." (PMID 24204789, 2013). "We found that rs11453459G (-G/GG) variant genotypes of PPP2R1A and the rs1255722AA variant genotype of PPP2R5E conferred increased risks of lung cancer (rs11453459, -G/GG vs. –: OR = 1.31, 95% CI = 1.13–1.51; rs1255722, AA vs. AG/GG: OR = 1.27, 95% CI = 1.07–1.51)." (PMID 24204789, 2013). "Furthermore, we observed a positively significant interaction between number of PPP2R1A and PPP2R5E risk genotypes and drinking status on increasing lung cancer risk (P = 0.034)." (PMID 24204789, 2013). "Our findings suggested that the two functional variants in PPP2R1A and PPP2R5E and their combination are associated with lung cancer risk in Chinese, which may be valuable biomarkers to predict risk of lung cancer." (PMID 24204789, 2013).
serous carcinomas (7 papers, 2014 to 2025). "This study found that uterine (type II) high-grade serous carcinomas exhibited a higher prevalence of PPP2R1A mutations compared with ovarian (type II) high-grade serous carcinomas." (PMID 39850502, 2025). "Their study revealed that uterine (type II) high-grade serous carcinomas have had higher prevalence of PPP2R1A mutations than ovarian (type II) high-grade serous carcinomas." (PMID 39850502, 2025).
uterine cancer (7 papers, 2018 to 2025). Primary or metastatic malignant neoplasm involving the uterine corpus and/or the cervix. "In uterine cancer, recurrent PPP2R1A mutations (P179R and S256F) drive tumorigenesis and metastasis, while in colorectal cancer, PPP2R1B (a paralog) inactivation promotes liver metastasis through ERK pathway activation." (PMID 41409293, 2025). "Similar mechanisms have been reported in other cancers: in uterine cancer, PPP2R1A mutations exert a dominant-negative effect by binding to TIPRL1, inhibiting PP2A activity, and activating oncogenic pathways such as AKT to promote malignant growth." (PMID 41409293, 2025). "Recurrent PPP2R1A mutations in uterine cancer act through a dominant-negative mechanism to promote malignant cell growth, We found one case of OCS also harboring it as a driver mutation." (PMID 39239274, 2024). "Mutations of PPP2R1A in uterine cancer affect oncogenic signaling and promote tumor cell growth, whereas EHHADH and ACAT1 are regulators of drug resistance in tumor cells; however, the role of VCP in cancer is unclear." (PMID 37373553, 2023). "The PPP2R1A mutation in uterine cancer was reported acting through a dominant-negative mechanism to promote cancer cell growth." (PMID 30027097, 2018). "It was previously shown that PPP2R1A mutation is frequent in uterine cancers." (PMID 37492373, 2023). "Mutations of PPP2R1A promote cells proliferation by upregulating the phosphorylation levels of Akt, ERK, and WNK1 in gastrointestinal stromal tumors and by interactions with the PP2A inhibitor TIPRL1 in uterine cancer." (PMID 34076143, 2021).
uterine serous carcinoma (7 papers, 2013 to 2025).
colon carcinoma (5 papers, 2013 to 2025). "Notably, we demonstrated for the first time that propolis treatment resulted in a 1.86-fold increase in PPP2R1A levels in the colon cancer cell line SW-620 compared with untreated cells." (PMID 39850502, 2025). "In malignant colon cancer cell lines, which display a highly activated WNT pathway, PPP2R1A is almost exclusively used to assemble the PP2A holoenzyme, while in normal colon cell lines, both the α and β scaffolds are present." (PMID 28619992, 2017).
Intellectual disability (5 papers, 2020 to 2025). "Pathogenic PPP2R1A variants were first described in 2015 by Houge and colleagues, who identified de novo missense variants in patients with severe intellectual disability and structural brain abnormalities." (PMID 41465181, 2025). "These mice exhibited impaired spatial learning and memory, resembling Ppp2r1a-associated intellectual disability." (PMID 40839403, 2025). "Our findings uncover an unexpected role of PPP2R1A in regulating endocannabinoid signaling, providing fresh molecular and synaptic insights into the mechanisms underlying intellectual disability." (PMID 40839403, 2025). "Recently, variants in PPP2R1A have been associated with syndromic intellectual disability and a consistent, but still expanding, phenotype." (PMID 37762002, 2023). "Children carrying genetic variants in the scaffolding subunit of the PP2A enzyme PPP2R1A exhibit symptoms typical of neurodevelopmental disorders, such as moderate-to-severe intellectual disability and developmental delay; but how PPP2R1A variants disrupt brain function has remained unclear." (PMID 40892513, 2025). "However, the precise mechanisms by which Ppp2r1a deficiency contributes to NDDs, particularly intellectual disability, remain poorly understood." (PMID 40839403, 2025). "Clinical studies showed that heterozygous loss-of-function mutations in PPP2R1A (e.g., P179L, R182W, S219L, and R258H) are linked to intellectual disability, suggesting that PPP2R1A haploinsufficiency may be a significant risk factor." (PMID 40839403, 2025). "Mutations in PPP2R1A, encoding the scaffolding subunit, are linked to intellectual disability, although the underlying mechanisms remain unclear." (PMID 40839403, 2025). "Our study establishes a causal link between Ppp2r1a haploinsufficiency and intellectual disability." (PMID 40839403, 2025). "Our data show that heterozygous deletion of Ppp2r1a in forebrain excitatory neurons (NEX-Cre; Ppp2r1af/+, NEX-het-conditional knockout [NEX-het-cKO]) in mice impaired spatial learning and memory, mimicking the intellectual disability phenotype associated with human PPP2R1A variants." (PMID 40839403, 2025). "Taken together, our results suggest that Ppp2r1a haploinsufficiency in forebrain excitatory neurons reduces anxiety levels and severely impairs spatial learning and memory, closely resembling the core symptoms of intellectual disability observed in patients harboring PPP2R1A mutations." (PMID 40839403, 2025). "We confirmed that Ppp2r1a haploinsufficiency in mice recapitulates spatial learning and memory deficits, validating this model for studying human intellectual disability." (PMID 40839403, 2025). "Clinically, pathogenic variants in PPP2R1A (encoding PP2A-A) and PPP2R5D (encoding PP2A-B) have been linked to NDDs characterized by severe intellectual disability, speech impairment, epilepsy, and developmental delay." (PMID 40839403, 2025). "Because mutations in multiple subunits, including PPP2R1A, PPP2R5B, PPP2R5C, and PPP2R5D, have been linked to intellectual disability, future studies will investigate their roles in eCB signaling and related neuropsychiatric disorders." (PMID 40839403, 2025). "Clinical studies have linked heterozygous loss-of-function mutations in PP2A subunits, including PPP2R1A and PPP2R5D, to intellectual disability, though the underlying mechanisms remain unclear." (PMID 40839403, 2025). "In our study, we asked whether Ppp2r1a dysfunction contributes to intellectual disability." (PMID 40839403, 2025). "After consolidating intellectual disability gene lists from two databases and one recent review article, we identified eight LRRK2 interacting proteins that have previously been linked to intellectual disability: ACTB, ACTG1, ATRX, DYNC1H1, HERC2, PPP2R1A, TUBA1A, and YWHAE." (PMID 31963867, 2020).
ovarian clear cell cancer (5 papers, 2012 to 2025). An invasive malignant neoplasm that arises from the ovary and is characterized by a predominance of clear and hobnail malignant epithelial cells. "The recent discovery that loss-of-function mutations in the gene encoding the protein phosphatase 2A (PP2A) scaffold protein PPP2R1A confer sensitivity to immune checkpoint blockade in ovarian clear cell carcinoma, therefore represents a breakthrough." (PMID 40737443, 2025). "Mutation of PPP2R1A has been observed at high frequency in endometrial serous carcinomas but at low frequency in ovarian clear cell carcinoma." (PMID 27272709, 2016). "Mutations in the PP2A regulatory subunit A component, PPP2R1A, have previously been shown in ovarian clear cell cancers." (PMID 22514011, 2012). "Molecular profiling of human endometrioid ovarian cancers revealed that the most prevalent mutations are similar to those observed in clear-cell ovarian cancer and include PIK3CA (40%), ARID1A (30%), KRAS (30%), PTEN (16%), and PPP2R1A (16%)." (PMID 32679669, 2020). "Previous studies showed that the somatic mutations of ovarian clear cell carcinoma (mainly in ARID1A, PIK3CA, KRAS and PPP2R1A) might be related to chromatin remodeling, cell proliferation, cell cycle checkpointing and cytoskeletal organization." (PMID 34680501, 2021).
developmental delay (4 papers, 2021 to 2025). "We present a case of a 14-month-old boy with infantile spasms, developmental delay, obstructive sleep apnea, PPP2R1A gene mutation, congenital hydrocephalus, hypoplastic/absent corpus callosum, pontocerebellar hypoplasia, and medically refractory seizures." (PMID 34984142, 2021).
hepatocellular carcinoma (4 papers, 2013 to 2025). A malignant tumor that arises from hepatocytes. "They suggested that PPP2R1A acted as a downstream effector in hepatoma, mitigating the enhanced cell migration driven by WNK1, a key protein kinase involved in tumor-induced angiogenesis." (PMID 39850502, 2025). "In their study, overexpression of PPP2R1A counteracted the cell migration induced by increased WNK1 levels in HepG2 hepatoma cells." (PMID 39850502, 2025). "The results suggest that PPP2R1A acts as a repressor of WNK1 in stimulating the migration of hepatoma cells." (PMID 36292952, 2022). "Overexpression of PPP2R1A can rescue the increased cell migration caused by WNK1 overexpression in HepG2, indicating that PPP2R1A is a downstream effector in hepatoma." (PMID 36292952, 2022). "Moreover, overexpression of PPP2R1A can eliminate the increased migration ability induced by WNK1 overexpression in hepatoma cells, supporting the tumor suppressor role of PPP2R1A." (PMID 36292952, 2022). "To further address the role of PPP2R1A in WNK1 in hepatoma cell migration, we transfected HepG2 cells with WNK1 and PPP2R1A, and co-cultured them with the HUVEC cells for a transwell migration assay." (PMID 36292952, 2022).
adenomyosis (3 papers, 2019 to 2025). The growth of endometrial tissue inside the muscular wall of the uterine corpus. "Although mutations in FBXW7, ARHGAP35, PIK3R1, and PPP2R1A were also detected in adenomyosis, their frequencies were not higher than those in the normal endometrium." (PMID 40679511, 2025). "The mutation frequencies per subject, regardless of sampling depths, were as follows: in adenomyosis, KRAS: 33.3%, PIK3CA: 14.3%, and ARID1A: 14.3%, and in uterine endometrium, KRAS: 66.7%, PIK3CA: 57.1%, ARHGAP35: 52.4%, PPP2R1A: 33.3%, PIK3R1: 28.6%, and FGFR2: 19.0%." (PMID 40679511, 2025).
Alzheimer disease (3 papers, 2021 to 2025). A progressive, neurodegenerative disease characterized by loss of function and death of nerve cells in several areas of the brain leading to loss of cognitive function such as memory and language. "PPP2R1A is associated with Alzheimer's disease (AD) and specific cognitive domains, and its mRNA and protein levels are elevated in the patient’s brain." (PMID 34837693, 2021). "In contrast, the PPP2R1A low-expression group exhibited enrichment in Alzheimer disease, apoptosis, Parkinson disease, protein export, and ribosomes." (PMID 41327671, 2025).
clear cell carcinoma (3 papers, 2014 to 2024). "The patient carried a typical genomic profile of clear cell carcinoma including mutations in KRAS, PPP2R1A, and PIK3R1." (PMID 38686193, 2024).
colorectal cancer (3 papers, 2020 to 2025). A primary or metastatic malignant neoplasm that affects the colon or rectum. "Mutations in other components of the pathway, including PTEN, TSC1, PPP2R1A, and MTOR, were also significantly more frequent in CDX2-suppressed colorectal cancers." (PMID 39452477, 2024).
endometrioid carcinoma (3 papers, 2017 to 2024). "Additionally, mutations at the PPP2R1A codon 258 have been observed in serous and endometrioid carcinomas as reported in several non-TCGA studies." (PMID 36945530, 2024).
endometrioid ovarian cancer (3 papers, 2020 to 2022). "A maximum of six mutations was present in one patient with endometrioid ovarian carcinoma (MSH6, PIK3CA, FBXW7, PIK3R1, PITCH1, ERBB3 and PPP2R1A)." (PMID 32120793, 2020).
alveolar rhabdomyosarcoma (2 papers, 2018 to 2021). A rapidly growing malignant mesenchymal neoplasm. "In alveolar rhabdomyosarcoma, silencing of PPP2R1A significantly increased cell growth, suggesting the tumor-suppressive function of PPP2R1A." (PMID 34076143, 2021).
bladder cancer (2 papers, 2016 to 2018). "In addition to the PIK3CA mutations, we found signatures 2 and 13 to be associated with ERBB2 p.S310F (c.929C>T) mutation in bladder cancer, and signature 13 to be associated with PPP2R1A p.P179R (c.536C>G) mutation in uterine corpus endometrial carcinoma." (PMID 30412573, 2018).
carcinosarcoma (2 papers, 2016 to 2023). A malignant tumor composed of a mixture of carcinomatous and sarcomatous elements.
gastric cancer (2 papers, 2025). A primary or metastatic malignant neoplasm involving the stomach. "While PPP2R1A is recognized as a tumor suppressor in certain cancers, emerging evidence suggests its potential oncogenic properties in gastric cancer (GC), where its silencing significantly inhibits proliferation, migration, and invasion while promoting apoptosis in GC cells (P < 0.01)." (PMID 41409293, 2025).
gastrointestinal stromal tumor (2 papers, 2021 to 2022). "PPP2R1A, the subunit of PP2A, has been reported to dephosphorylate and inactivate WNK1, while mutant PPP2R1A increases pWNK in gastrointestinal stromal tumors." (PMID 36292952, 2022).
lung adenocarcinoma (2 papers, 2016 to 2025). A carcinoma that arises from the lung and is characterized by the presence of malignant glandular epithelial cells. "Based on bioinformatics predictions, PPP2R1A is closely linked to the progression of lung adenocarcinoma." (PMID 41409293, 2025). "Subsequently, Further assessment of PPP2R1A’s diagnostic potency in lung adenocarcinoma yielded an AUC of 0.593 (95% CI: 0.54-0.64), indicating modest discriminative capacity for malignant identification." (PMID 41409293, 2025). "Based on TCGA-LUAD data, the mutation frequency of PPP2R1A in lung adenocarcinoma was only 2.3%, primarily consisting of missense mutations in the phosphatase domain (e.g., Q372L)." (PMID 41409293, 2025). "Kaplan-Meier (KM) survival analysis showed that PPP2R1A overexpression in patients with lung adenocarcinoma was significantly associated with poor FP and OS outcomes." (PMID 41409293, 2025). "The expression level of PPP2R1A was closely associated with N stage in lung adenocarcinoma patients, compared with N0 and N1 stage lung adenocarcinoma patients, PPP2R1A expression levels were significantly higher in N2 stage lung adenocarcinoma patients." (PMID 41409293, 2025). "Finally, we used the cBioPortal platform to investigate the genetic mutation characteristics of PPP2R1A in lung adenocarcinoma." (PMID 41409293, 2025). "PPP2R1A expression was significantly associated with lung adenocarcinoma stage; advanced-stage (III-IV) LUAD patients exhibited significantly higher PPP2R1A expression compared to early-stage (I-II) cases." (PMID 41409293, 2025). "In this study, we conducted a comprehensive analysis of the PPP2R1A gene expression in lung adenocarcinoma (LUAD), exploring its role in tumor progression, prognosis, and immune modulation." (PMID 41409293, 2025). "Despite these findings in various malignancies, the role of PPP2R1A in lung adenocarcinoma (LUAD) remains poorly characterized compared to other PP2A subunits like PPP2R2A, which regulates EMT in NSCLC." (PMID 41409293, 2025). "Paired analysis results were consistent with unpaired results, further confirming that PPP2R1A expression levels were significantly increased in lung adenocarcinoma samples (P < 0.05)." (PMID 41409293, 2025). "Subgroup analysis based on clinical pathological parameters further revealed the relationship between PPP2R1A and the clinicopathological features of lung adenocarcinoma." (PMID 41409293, 2025). "In the TCGA lung adenocarcinoma cohort, PPP2R1A expression demonstrated significant positively correlated with PRPF31 (R = 0.72), SCAF1 (R = 0.72), and PTOV1 (R = 0.71)." (PMID 41409293, 2025). "This study unveils the dual role of PPP2R1A in lung adenocarcinoma (LUAD) through a multidimensional approach: it serves as both a molecular driver of tumor progression and a key regulator of the immune microenvironment." (PMID 41409293, 2025). "Unpaired analysis results showed a significant upregulation of PPP2R1A in lung adenocarcinoma." (PMID 41409293, 2025). "However, our analysis in lung adenocarcinoma reveals that it functions as an oncogene, suggesting that PPP2R1A is subject to complex regulation in tumors." (PMID 41409293, 2025).
ovarian endometriosis (2 papers, 2023 to 2025). A non-neoplastic disorder characterized by the growth of endometrial tissue in the ovaries. "Our previous study clarified that PIK3CA, ARID1A, KRAS, FBWX7, and PPP2R1A are also frequently mutated in ovarian endometriosis." (PMID 38067342, 2023). "Another study revealed that somatic mutations specifically in cancer-associated genes were observed in 4% of ovarian endometriosis samples, including KRAS p.G12V and PPP2R1A p.S256F along with two ARID1A nonsense mutations, p.Q403 * and p.G1926 *." (PMID 40364006, 2025).
pancreatic cancer (2 papers, 2018 to 2024). "For example, it has been reported that inhibition of PPP2R1A radiosensitizes pancreatic cancer via activation of CDC25C/CDK1, thus, PPP2R1A is a target gene for local therapy of pancreatic cancer." (PMID 29697368, 2018). "PPP2R1A, a well-characterized scaffold subunit of the PP2A complex, has been reported to decrease the cytotoxicity of chemoradiation treatment in pancreatic cancer via activating HRR and inhibiting CDC25/and CDK1." (PMID 38654331, 2024).